IATPR (ITGB1 adjacent tumor promoting lncRNA)
Synonyms: TCONS_00018476; linc-ITGB1
Gene: Long non-coding RNA gene on chromosome 10 (33,055,799 to 33,116,817, reverse strand). Ensembl gene ENSG00000233387.
Diseases named in the same sentence as IATPR in open-access papers:
IATPR is named in the same sentence as 2 diseases in open-access papers, as found by Europe PMC text mining. Sharing a sentence is not in itself a finding about the gene and the disease.
IATPR shares sentences with these, for which no sentence is quoted: cancer (1 paper); prostate tumour (1).